SNUPN (snurportin 1)
Description:
Functions as an U snRNP-specific nuclear import adapter. Involved in the trimethylguanosine (m3G)-cap-dependent nuclear import of U snRNPs. Binds specifically to the terminal m3G-cap U snRNAs.
Synonyms: RNUT1; SNURPORTIN-1; Snurportin1; KPNBL; LGMDR29
Tractability: Small molecule: a structure with a bound ligand is known; it has a high-quality binding pocket. Antibody: its Gene Ontology location is reachable by antibodies, with high confidence. PROTAC: ubiquitination databases record sites on it; its protein half-life has been measured.
Gene: Protein-coding gene on chromosome 15 (75,598,083 to 75,626,469, reverse strand). Ensembl gene ENSG00000169371.
Subcellular location: Nucleus; Cytoplasm
Subcellular location (Human Protein Atlas): Cytosol; Nucleoplasm; Plasma membrane
Pathways (Reactome):
Metabolism of RNA: snRNP Assembly
Gene Ontology:
Molecular function: protein binding; RNA cap binding; nuclear import signal receptor activity
Biological process: cytoskeleton organization; protein complex oligomerization; protein tetramerization; RNA import into nucleus; protein import into nucleus; snRNA import into nucleus
Cellular component: cytoplasm; cytosol; NLS-dependent protein nuclear import complex; nucleoplasm; nucleus; nuclear pore
Genetic constraint (gnomAD): Loss-of-function variants: 13 observed, 25.9 expected, observed/expected ratio (o/e) 0.5, 90% interval 0.33 to 0.8. The upper end of that interval is the gene's LOEUF score, 0.8, which puts it in group 3 of 6, group 1 being the genes least tolerant of losing a copy. Missense variants: 311 observed, 376.25 expected, observed/expected ratio (o/e) 0.83, 90% interval 0.75 to 0.91. Synonymous variants: 109 observed, 140.76 expected, observed/expected ratio (o/e) 0.77, 90% interval 0.66 to 0.91.
Gene-disease validity (ClinGen):
ClinGen rates the evidence that SNUPN causes each of these diseases.
SNUPN-related muscular dystrophy with or without multi-system involvement (autosomal recessive): Strong. A form of congenital muscular dystrophy in which the cause of the disease is pathogenic variation in the SNUPN gene.
Homologues: Orthologues: chimpanzee SNUPN (99% identical), macaque SNUPN (98% identical), pig SNUPN (94% identical), mouse Snupn (92% identical), dog SNUPN (91% identical), rabbit SNUPN (91% identical), guinea pig SNUPN (88% identical), rat Snupn (72% identical), tropical clawed frog snupn (66% identical), zebrafish snupn (64% identical), Caenorhabditis elegans F23F1.5 (36% identical), Drosophila melanogaster Snup (31% identical), and 1 more.
Diseases named in the same sentence as SNUPN in open-access papers:
SNUPN is named in the same sentence as 10 diseases in open-access papers, as found by Europe PMC text mining. Sharing a sentence is not in itself a finding about the gene and the disease. The quoted sentences say what the papers report.
breast carcinoma (3 papers, 2020 to 2023). "Among the 5 plasma proteins, SNUPN, CSK, and PARK7 emerged as “Strong” negatively causative associated proteins, indicating a protective effect against breast cancer development." (PMID 38304232, 2023). "Overall, we found 5 proteins (PEX14, CTSF, SNUPN, CSK, PARK7) with strong causal links to breast cancer." (PMID 38304232, 2023). "The results showed that 17 m7GRGs were risk factors and significantly impacted breast cancer prognosis, whereas NUDT10, NUDT3, EIF4E3, SNUPN, NUDT16, IFIT5 and EIF3D were favourable prognostic factors." (PMID 37353728, 2023). "Of these, genes hypothesized to have a tumor-suppressor function included LINC00886, MAN2C1, SNUPN, and STC1, while YBEY, SEMA4A, and MUTYH may have an oncogenic role in breast carcinogenesis based on their associations with breast cancer risk." (PMID 32139696, 2020). "The remaining 3 proteins, SNUPN (OR = 0.905, p < 0.001), CSK (OR = 0.962, p = 0.038), and PARK7 (OR = 0.954, p < 0.001), all exhibited negative causations with breast cancer." (PMID 38304232, 2023).
melanoma (2 papers, 2016 to 2022). A malignant, usually aggressive tumor composed of atypical, neoplastic melanocytes. "ACSL3 was coexpressed with SNUPN, TRIP13, and SEMA5A in melanoma." (PMID 27171439, 2016).
muscular dystrophies (2 papers, 2024 to 2025). "Here the authors report that recessive SNUPN mutations cause a distinct subtype of childhood muscular dystrophy and reveal SNURPORTIN-1’s role in muscle homeostasis, offering insights for new therapeutic strategies." (PMID 38413582, 2024). "Consequently, the identification of SNUPN as a gene causing muscular dystrophy adds to the complexity of recessive inherited muscular dystrophies and delineates an additional functional subtype potentially associated with dystroglycanopathy or other LGMD types." (PMID 38413582, 2024).
epilepsy (1 paper, 2025). A brain disorder characterized by episodes of abnormally increased neuronal discharge resulting in transient episodes of sensory or motor neurological dysfunction, or psychic dysfunction. "In this work, we screened five key m7G regulators in epilepsy and created a nomogram based on them to predict the risk of epilepsy, including METTL1, NUDT3, EIF4E3, LSM1, and SNUPN." (PMID 40658715, 2025). "Patients with epilepsy were more likely to exhibit aberrant expression of SNUPN, LSM1, and IFIT5." (PMID 40658715, 2025). "Gene expression analysis of datasets GSE143272 and GSE190452 identified 8 differentially expressed m7G regulators (NUDT3, EIF4E3, LARP1, IFIT5, SNUPN, METTL1, EIF4A1, and LSM1) in epilepsy." (PMID 40658715, 2025). "The boxplot revealed that epilepsy patients had up-regulated expression levels of NUDT3, EIF4E3, LARP1, IFIT5, and SNUPN, and down-regulated expression levels of METTL1, EIF4A1, and LSM1." (PMID 40658715, 2025).
tumor (8 papers, 2018 to 2024). "In addition to NUDT16 being a protective factor, the other three genes (WDR4, EIF4E2, and SNUPN) are risk factors that accelerate tumor progression." (PMID 38987843, 2024). "Correspondingly, there were some genes that were part of the CAP formation genes, such as NCBP3, NUDT4, CYFIP2, SNUPN, and EIF4E2, which were weakly expressed in most tumor tissues and highly expressed in normal tissues." (PMID 36226166, 2022).
cancer (3 papers, 2020 to 2022). A tumor composed of atypical neoplastic, often pleomorphic cells that invade other tissues. "Few studies have investigated the mechanistic roles of LINC00886, SNUPN and SEMA4A in cancer initiation." (PMID 32139696, 2020).
SNUPN also shares sentences with these, for which no sentence is quoted: Azoospermia (1 paper); dystroglycanopathy (1); gallbladder cancer (1); glioma (1).